CDKN2A (cyclin dependent kinase inhibitor 2A)
Diseases named in the same sentence as CDKN2A in open-access papers (continued):
Sharing a sentence is not in itself a finding about the gene and the disease.
sarcoma (continued). "In regards to the prognostic impact of CDKN2A loss in sarcoma, previous work had suggested that its loss might have prognostic significance in Ewing’s sarcoma, however, a large analysis of 568 Ewing’s patients enrolled on a Children’s Oncology Group (COG) protocol, failed to reproduce this finding." (PMID 31528332, 2019). "In sarcomas, CDKN2A alterations, reported in 71% of EWSR1::PATZ1 fusion cases in a series of 11 patients, are associated with aggressive phenotypes and poorer outcomes." (PMID 40575153, 2025). "CDKN2A/B deletions and correspondingly low levels of CDKN2A mRNA have been reported in high-grade endometrial sarcomas and pediatric sarcomas with BCOR genetic alterations." (PMID 41155410, 2025). "The second most common alteration in FUS/EWSR1-TFCP2 sarcomas, with an incidence of 75%, were deletions or indels of the CDKN2A tumor suppressor, which have been noted previously." (PMID 38168093, 2024). "The second condition was simplicity: any overexpression of CDK4 and equal or underexpression of CDKN2A for the tested sarcoma against the RNA pool, accomplished with the biomarker selection." (PMID 37875500, 2023). "There was a greater decrease in CDKN2A mRNA in sarcomas derived of older than younger individuals (adjusted mRNA-CNA-age p = 0.024)." (PMID 35017538, 2022). "It has been reported that 10%–22% of Ewing sarcoma and 20% of all sarcoma types have a CDKN2A deletion." (PMID 36003796, 2022). "This study demonstrated that palbociclib appears to be a clinically promising agent for Ewing sarcoma and possibly other sarcomas that have a CDKN2A deletion." (PMID 36003796, 2022). "Five genes are expressed only in this type of sarcoma: PIK3CA, MDM2, HMGA2, EGFR, CDK, CDK4, while CDKN2A is implicated in angiosarcomas and undifferentiated pleomorphic sarcomas only." (PMID 34359782, 2021). "Although the underlying mechanisms remain elusive, this finding prompted us to knockdown Cdkn2a in endometrial organoids, which unexpectedly led to the Kras-dependent development of CS or sarcoma." (PMID 34172714, 2021). "In this subtype of sarcoma, CDKN2A firmly connects to MDM2, CCND1, PIK3CA, CDK4, CBX7, and less firmly to EGFR, and IL-6." (PMID 34359782, 2021). "One of the most commonly altered CDK inhibitor genes in sarcomas is CDKN2A, which plays a complex and uniquely important role in tumor suppression." (PMID 32344731, 2020). "Other studies have identified whole‐genome duplication as a cause of the structural complexity of UPS, and CDKN2A alterations as a predictor of worse overall survival across sarcoma subtypes." (PMID 33047515, 2020). "Histological distributions of all sarcoma patients compared with patients with aberrant CDKN2A, showed an increase in the representation of UPS, MPNST, and MFS patients, and a decrease in the amount of LMS and LPS patients in those with CDKN2A loss." (PMID 31528332, 2019). "Genomic profiles of 7733 STS from the Foundation Medicine database were used to assess the frequency of CDKN2A alterations in histological subtypes of sarcoma." (PMID 31528332, 2019).
sarcoma (continued). "Homozygous deletions of the CDKN2A locus has been reported in the majority of human tumors including sarcomas." (PMID 26987019, 2016). "Conversely, in a Cdkn2a null background all mice developed sarcoma, 92% of which classified as ERMS and only 8% as UPS." (PMID 26987019, 2016). "This suggested that together with losses at Cdkn2a and Nf1 loci the recurrent duplications of these chromosomes belong to early events in sarcoma development." (PMID 21533183, 2011). "The fourth gene deregulated in TFCP2-rearranged sarcoma, besides ALK, CDKN2A, and MTAP, is TERT, encoding the catalytic component of the telomerase complex that protects dividing cells from progressive telomere shortening, subsequent senescence, and malignant transformation." (PMID 38168093, 2024). "To determine the tumorigenic potential of Cdkn2a loss, we bred Tek-Cre;Cdkn2aFlox/Flox mice lacking P3F and exclusively observed mononuclear phagocytic sarcomas." (PMID 37968277, 2023). "Hence, a plethora of alterations beyond CDK4/6 genes emerges as highly relevant for sarcoma pathobiology, providing several potential actionable targets at various steps of the CDKN2A-CCND-CDK4-RB axis." (PMID 36741019, 2023). "Intriguingly, CDKN2A loss in sarcoma was not itself significantly associated with a change in mRNA, but did significantly interact with age (Fig. 3Cbottom)." (PMID 35017538, 2022). "Interestingly, this research has pointed to the role of the gene coding for methylthioadenosine phosphorylase, often codeleted with p16 (CDKN2A), particularly in MM and several types of sarcomas." (PMID 33207594, 2020). "CDKN2A appeared in sarcoma and pancreatic adenocarcinoma groups." (PMID 32188081, 2020). "Taken together, TFCP2-rearranged sarcoma likely represents a separate entity characterized by distinct transcriptional and DNA methylation profiles, an unusual degree of genomic instability, truncated ALK variants, ALK and TERT overexpression, and recurrent CDKN2A/MTAP co-deletions." (PMID 38168093, 2024). "These clinical reports are in line with the observation that in MD mice, sarcomas share nonrandom genomic alterations including frequent loss of TS (such as Cdkn2a or Nf1), amplifications of oncogenes (Met, Jun), recurrent duplications of whole chromosomes 8 and 15, and DNA damage." (PMID 35790299, 2022). "The detection of a CDKN2A deletion has been recognized in a recent study as a potential biomarker for poor prognosis in soft tissue sarcomas, including subtypes such as SS, malignant peripheral nerve sheath tumor, sarcoma NOS, and undifferentiated pleomorphic sarcoma." (PMID 35639915, 2022).
sarcoma (continued). "The findings from this single-arm, phase II trial suggest that palbociclib has activity in advanced sarcomas other than WD/DD-LPS selected by RNA expression of CDK4 and CDKN2A, showing a promising median PFS and OS in a heavily pretreated population." (PMID 37875500, 2023). "Palbociclib was active in a variety of sarcoma subtypes, selected by CDK4/CDKN2A, and deserves further investigation in the sarcoma context." (PMID 37875500, 2023). "From December 2018 to November 2021, 96 patients with advanced and progressing sarcomas were screened for CDK4 and CDKN2A RNA expression in a baseline biopsy and assessed for eligibility." (PMID 37875500, 2023). "In fact, reduced expression of CDKN2A (a tumor suppressor protein similar to CDKN2B), has been observed in sarcoma progression and correlated with reduced patient survival." (PMID 29383146, 2017). "As differentiation markers for the UPS/MFS cluster (sarcoma cluster 4) DMRT2, ZNF217 and CDKN2A were selected for comparison with sarcoma cluster 1 (mainly DDLS samples), sarcoma cluster 2 (LMS samples) and sarcoma cluster 4 (mainly PLS samples), respectively." (PMID 24345474, 2013). "Notably, copy numbers (CNs) for cyclin-dependent kinase inhibitor (CDKN) 2A (CDKN2A) and CDKN2B in the sarcoma tissue were 0.6 and 0.5, respectively." (PMID 40416963, 2025). "In addition, a large-scale study of 77 radiotherapy-induced sarcomas reported a higher frequency of c-MYC amplification and losses of CDKN2A and CDKN2B in radiotherapy-induced sarcomas than in sporadic sarcomas." (PMID 41007286, 2025). "Preclinical investigators of this study found that CDK4 overexpression, while not of CDKN2A, was the most consistent predictive factor for palbociclib efficacy in sarcomas." (PMID 37875500, 2023). "Despite the fact that a valuable predictive biomarker selection for CDK4/6 inhibition is challenging, the selected biomarkers with RNA overexpression of CDK4 and no overexpression of CDKN2A seem adequate for future studies with CDK4/6 inhibitors in sarcomas." (PMID 37875500, 2023). "Similarly, multiple sarcoma subtypes, including UPS and MPNST, disrupt CDKN2A in early stages of their development to promote unrestricted growth and cellular transformation." (PMID 32344731, 2020). "We previously reported on a customized shRNA-based proliferation screen, which tested the contributions of 141 sarcoma-relevant genes, previously identified by transcriptional profiling of genetically engineered mouse sarcomas driven by KRAS(G12v) and CDKN2A deletion." (PMID 32898143, 2020).
sarcoma (continued). "The following genes were overexpressed in various tumors: CCND1 in colorectal and renal cancers, and sarcoma; CCNE1 in colorectal, lung, stomach, esophagus, head and neck, uterine and ovarian cancers, and sarcoma; and CDKN2A in lung, uterine, and ovarian cancers." (PMID 28258440, 2017). "from West China Hospital identified co-amplification of 12q15 and 12p13, as well as CDKN2A/2B deletion, in one case of FS-DFSP; these genetic aberrations were confined to the fibrosarcomatous component, suggesting a synergistic role in the progression to sarcoma." (PMID 39600645, 2024). "Indeed, consistent with the premature senescence phenotype and the increased expression of Ink4a and Arf in sarcoma-iPSC MEFs, EWS/ATF1 binding was detectable at Cdkn2a locus in sarcoma-iPSC MEFs but not in G1297." (PMID 31488818, 2019). "Finally, our findings suggest that patients with TFCP2-rearranged sarcomas, which are refractory to conventional chemotherapy, may benefit from combination treatments that include platinum derivatives, ALK inhibitors, and, in the case of CDKN2A/MTAP co-deletions, drugs targeting PRMT5." (PMID 38168093, 2024). "In comparison with data regarding PATZ1-fused sarcoma, the PATZ1-fused CNS tumors in this series were not enriched for homozygous deletions mapping to the CDKN2A/B locus (observed in only 2/59 cases, 3%)." (PMID 34417833, 2021). "Indeed, it would be valuable to determine the clinical outcome, in terms of PFS and OS, of an advanced and progressing independent sarcoma population exhibiting overexpression of CDK4, without overexpression of CDKN2A." (PMID 37875500, 2023). "A candidate set of 141 sarcoma-relevant genes, identified by transcriptional profiling of genetically engineered mouse RMS and non-myogenic sarcomas driven by KRAS(G12v) and CDKN2A deletion, was previously published." (PMID 32898143, 2020). "However, some of the sarcomas may carry promoter methylation of RB1 and/or CDKN2A, resulting in the inactivation of either gene that is not identified by the NGS." (PMID 33924080, 2021).
prostate carcinoma (93 papers, 1996 to 2025). A carcinoma that arises from epithelial cells of the prostate gland. "The expression of CDKN2A encoding the cell cycle inhibitor p16 has been shown to correlate with the induction of cellular senescence in prostate cancer cells." (PMID 40072554, 2025). "DU145 cells have genetic mutations in two commonly mutated tumor suppressor genes, RB1 and CDKN2A, which likely contribute to the transformation of this prostate cancer cell line." (PMID 25030902, 2014). "It was reported that genetic and epigenetic aberrations of CDKN2A resulted in enhanced carcinogenesis and poor prognosis in various cancers, such as ovarian cancer, lymphoma, and prostate cancer, etc." (PMID 37428205, 2023). "Genetic and epigenetic aberrations of CDKN2A lead to enhanced carcinogenesis and poor prognosis in various cancer types including lymphoma, skin cancer, ovarian cancer, and prostate cancer." (PMID 34331411, 2021). "PIK3R5, TBX2 and TWIST1 gene were found to be hypermethylated in all four cancers, while CDKN2A (ARF) is hypermethylated in colorectal and prostate cancers." (PMID 33143142, 2020). "ARF (alternate reading frame protein product of the CDKN2A locus) protein was found to induce the SUMOylation of Slug at Lysine 192, and it potentially lead to increased migration in prostate cancer cells." (PMID 30096838, 2018). "PSP94 is a suppressor of tumor growth and metastasis; SLIT2 inhibits prostate cancer cell proliferation and invasion; and CDKN2A is a critical tumor suppressor gene." (PMID 28410242, 2017). "We also found >2 fold signal in genes previously identified as methylated in prostate cancer such as CDKN2A (average of 15.8 fold enrichment), RUNX3 (2.8 fold), and PTGS2 (2.9 fold)." (PMID 19283074, 2009). "In particular, CDKN2A is more frequently methylated in prostate cancer tissue compared with normal tissue, suggesting that p16INK4A expression may be epigenetically suppressed in malignant lesions." (PMID 41157576, 2025). "Our results provide new mechanisms how CDKN2A influences cell proliferation in prostate cancer." (PMID 33174391, 2020). "We also measured promoted expression of CDKN2A in prostate cancer lines." (PMID 29444163, 2018). "Also, PSP94, SLIT2 and CDKN2A are downstream targets of EZH2 in prostate cancer that mediates tumorigenesis and metastasis." (PMID 28410242, 2017). "Increased occurrence of prostate cancer metastasis was also shown to be present in patients with co-deletion of STAT3 and CDKN2A." (PMID 32585812, 2020). "The most common actionable genetic alterations in the prostate cancer cohort included: 6 DNA damage repair altered tumors (55%), 4 PTEN (36%), 4 AR receptor (36%), 3 CCND1 (27%), 2 CDKN2A (18%), and 2 FGF family altered tumors (18%)." (PMID 30551737, 2018). "In fact, CDKN2A, ADRB2, CDH1 and SLIT2 were reported to be suppressed by EZH2 in prostate cancer cells and were also targeted by EZH2 in at least one prostate cell line in our ChIP sequencing analysis." (PMID 27835578, 2016). "The observed interaction between HNF1B with CDKN2A contributes to suppression of SMAD6 and TGF‐β signalling, which suggests that HNF1B may play important roles in prostate cancer initiation and progression." (PMID 33174391, 2020). "Moreover, in prostate cancer, EZH2 can repress the expression of tumor suppressors such as DAB2IP, p16 (CDKN2A), CDK4, E-cadherin (CDH1), MSMB, Ras (KRAS), NF-κB (NFKB1), EMT regulator." (PMID 27835578, 2016). "As examples, methylation of the CDKN2A promoter has been detected in sputum of smokers up to 3 years before they were diagnosed with cancer, GSTP1 has been used in prostate cancer detection, and RASSF1A can be detected in serum from gastric colorectal adenocarcinoma patients." (PMID 22570110, 2012).
prostate carcinoma (continued). "Also, other hypermethylated genes, including CDH1, CDKN2A, CD44, CAV1, HOXD3, and BMP7, have been demonstrated in prostate cancer." (PMID 20671914, 2010). "BMI1 also possesses functions independent of CDKN2A repression, including the regulation of genes involved in differentiation and cell contact inhibition in Ewing sarcoma and androgen receptor expression in prostate cancer." (PMID 33523558, 2021).